NDUFS1 (NADH:ubiquinone oxidoreductase core subunit S1)
Diseases named in the same sentence as NDUFS1 in open-access papers (continued):
Sharing a sentence is not in itself a finding about the gene and the disease.
diabetes (2 papers, 2023 to 2025). "Ndufs1 expression was reduced with diabetes as seen in the LV and RV, and Sdha appeared to be elevated mildly but significantly in KO non‐diabetic atria." (PMID 38054572, 2023). "In particular, ERRα and Ndufs1 were significantly reduced in diabetes compared to control animals, as observed in the LV." (PMID 38054572, 2023). "NDUFS1 exhibits a negative correlation with IL6 and TNF, suggesting a potential link to inflammatory processes in the context of diabetes or sarcopenia." (PMID 40869253, 2025).
glioma (2 papers, 2020 to 2025). A benign or malignant brain and spinal cord tumor that arises from glial cells (astrocytes, oligodendrocytes, ependymal cells). "We established that OSMR directly interacts with NDUFS1/NDUFS2 of complex I in the mitochondria of patient derived glioma stem cells." (PMID 32807793, 2020). "GYS1, NDUFA11, OXSM, RPN1, and SLC3A2 play a role in promoting cancer in glioma, while LRPPRC, NCKAP1, NDUFS1, NUBPL and SLC7A11 play a role in inhibiting tumour." (PMID 39993959, 2025).
heart failure (2 papers, 2021 to 2022). Inability of the heart to pump blood at an adequate rate to meet tissue metabolic requirements. "First, we started from the available public database and found that the expression of Ndufs1 was decreased in the left heart of patients with heart failure." (PMID 35817848, 2022). "In the present study, we found that Ndufs1 expression was significantly decreased in the hearts of heart failure patients and mice after MI." (PMID 35817848, 2022). "We believe this AAV9-mediated Ndufs1 gene therapy approach can be applied for patients with post-MI heart failure and other cardiovascular diseases." (PMID 35817848, 2022). "Given that mitochondrial function and cardiomyocyte apoptosis are closely related to heart failure after MI, the results of this study suggest that targeting Ndufs1 may be a potential therapeutic strategy to improve cardiac function in patients with heart failure." (PMID 35817848, 2022). "However, whether Ndufs1 plays a role in the pathological processes of heart failure after MI is unknown." (PMID 35817848, 2022). "Ndufs1 has been illustrated to play a central role in the regulation of morphological dynamics and oxidative stress and may play an important role in mitochondrial crista remodeling, cytochrome release, and mitochondrial respiration in the development of CH and heart failure." (PMID 33763166, 2021).
infertile (2 papers, 2019 to 2021). "Hence, NDUFS1 may serve as potential diagnostic biomarker to access the mitochondrial function in idiopathic infertile men under the antioxidant treatment." (PMID 31623114, 2019).
melanoma (2 papers, 2023 to 2024). A malignant, usually aggressive tumor composed of atypical, neoplastic melanocytes. "2D proteomic analysis also identified a differential representation of NDUFS1 (core component of ETC Complex I) and TUFM (mitochondrial translation regulator) proteoforms, suggesting mTORC2 regulation on mitochondrial dynamics in melanoma." (PMID 38755661, 2024). "As an interacting partner with mitochondrial OSMR or CD147, NDUFS1/2 or NDUFS6 confers their individually roles in mediating oxidative phosphorylation related IR resistance of brain tumor stem cells, or in regulating complex I activity and apoptosis in human melanoma, respectively." (PMID 37469574, 2023).
non-alcoholic fatty liver disease (2 papers, 2018 to 2023). "Six of the key metagenes—INSR, MAP3K5, NDUFB8, NDUFS1, SDHB, and UQCRC2—are involved in nonalcoholic fatty liver disease (hsa04932), which is caused by a defect in insulin suppression of free fatty acid (FAA) disposal due to the induction of insulin resistance." (PMID 36979367, 2023).
adenovirus infection (1 paper, 2025). "We found that re-expression of WT Ndufs1 increased free complex I levels and activity at 48 and 72 h post-adenovirus infection, compared to AdGFP controls, while compared to WT Ndufs1, expression of C92D mutant Ndufs1 significantly increased respirasome complex I levels and activity at 48 and 72 h." (PMID 40752580, 2025).
chronic heart failure (1 paper, 2021). "Patients with combined chronic heart failure and diabetes mellitus have worse prognoses associated with elevated ROS overproduction but decreased SOD2/NDUFS1 expression rates compared to patients with chronic heart failure without diabetic history." (PMID 33686350, 2021).
colitis (1 paper, 2024). Inflammation of the colon. "We further tested the mRNA and protein levels of the characterized genes in the intestinal mucosa of DSS-induced colitis mice and UC patients, and the results showed that the mRNA and protein levels of SLC7A11, NDUFS1, LRPPRC, and CD2AP were dramatically downregulated in DSS-induced colitis mice." (PMID 38977802, 2024).
colorectal tumor (1 paper, 2024). "Variants in this gene in colorectal tumor cells lead to a loss of OXPHOS and result in disordered proliferation, likely due to NDUFS1′s essential role in initiating phosphorylation." (PMID 39684297, 2024).
COVID-19 (1 paper, 2023). A disease caused by infection with severe acute respiratory syndrome coronavirus 2. "Mitochondrial proteins such as ATP5A1, CYB561D1, several CYP accessions, L2HGDH, two MRP, MRPL37, NDUFS1 and others showed increased observation frequency across COVID-19 and ICU-ARDS versus NHP individually by the Chi Square test (χ2 ≥ 10, p ≤ 0.01) and as a group by one way ANOVA (p ≤ 0.003)." (PMID 37031181, 2023).
Cyanosis (1 paper, 2022). Bluish discoloration of the skin and mucosa due to poor circulation or inadequate oxygenation of arterial or capillary blood. "Here, we describe lip cyanosis as the first symptom of mitochondrial respiratory chain complex I deficiency (MCID)-related LS, caused by a compound heterozygous mutation in NDUFS1." (PMID 36042640, 2022).
development delay (1 paper, 2023). "The NDUFS1 carrier presents with motor development delay, intellectual disability, seizure with diffuse cerebral and cerebellar WMH." (PMID 37981684, 2023).
diabetic retinopathy (1 paper, 2021). "Oxidative stress and mitochondrial dysfunction were involved in the pathogenesis of diabetic retinopathy, we hypothesized that NDUFS1 might play an important role in DR." (PMID 34603851, 2021).
dilated cardiomyopathy (1 paper, 2019). Cardiomyopathy which is characterized by dilation and contractile dysfunction of the left and right ventricles. "We identified genes that have previously been implicated in heart development and structural heart malformations (e.g. MBNL1, ROR1), and known disease-related genes (e.g. NEXN, dilated cardiomyopathy; NDUFS1, mitochondrial complex I deficiency)." (PMID 31314787, 2019).
endometriosis (1 paper, 2025). The growth of functional endometrial tissue in anatomic sites outside the uterine body. "NDUFS1 (OS) is thought to be associated with malignant transformation in endometriosis, whereas the role of RPL12 warrants more research." (PMID 40778374, 2025).
Insulin resistance (1 paper, 2025). Increased resistance towards insulin, that is, diminished effectiveness of insulin in reducing blood glucose levels. "Over-stabilized MDM2 induces cytoplasmic accumulation of NDUFS1, disrupting mitochondrial super-complex assembly, enhancing ROS production, and initiating BIM-mediated BAK/BAX-dependent apoptosis—events that lead to insulin resistance." (PMID 41459066, 2025).
intraepithelial neoplasia (1 paper, 2021). A precancerous neoplastic process that affects the squamous, glandular, or transitional cell epithelium without evidence of invasion. "Transcript levels of both, NDUFS1 and ATP5O, were significantly enhanced in intraepithelial neoplasia and PCa compared to benign prostate glands (p < 0.05)." (PMID 34885151, 2021).
ischemia reperfusion injury (1 paper, 2024). Adverse functional, metabolic, or structural changes in ischemic tissues resulting from the restoration of blood flow to the tissue (reperfusion), including swelling; hemorrhage; necrosis; and damage from free radicals. "Recent work has shown AAV-mediated overexpression of mitochondrial complex CI core subunit S1 (Ndufs1) and assembly factor Ndufab1 to be cardioprotective against ischemia-reperfusion injury in mice." (PMID 39446877, 2024).
ischemic cardiomyopathy (1 paper, 2022). Ischemic cardiomyopathy is a cardiomyopathy in which a weakness in the muscle of the heart due to inadequate oxygen delivery to the myocardium with coronary artery disease being the most common cause. "Scatter plot analysis showed a significant positive correlation between Ndufs1 and Sp1 mRNA levels in NF subjects and HF patients; similar results were obtained in patients with ischemic cardiomyopathy." (PMID 35817848, 2022).
kidney cancer (1 paper, 2023). Primary or metastatic malignant neoplasm involving the kidney. "These two databases consistently displayed that NDUFS1 expression was significantly downregulated in the majority of tumor tissues, especially decreased in kidney cancers, including KIRC, KIRP and KICH." (PMID 37469574, 2023). "As for kidney cancer, NDUFS1 was reported to be increased in 1 study while decreased in 5 studies." (PMID 37469574, 2023).
lung injury (1 paper, 2025). "In conclusion, our research found that NDUFS1 was declined in alveolar epithelial cells during PQ/LPS-induced acute lung injury, which impaired ENaCα and alveolar fluid clearance." (PMID 40860777, 2025). "Our study first discovered that NDUFS1 played an important role in regulating ENaCα, which may provide a new idea for therapy of acute lung injury and other diseases." (PMID 40860777, 2025).
lymph node metastasis (1 paper, 2023). "The correlation of NDUFS1 with clinicopathological variables of GC, such as gender and age of patients, as well as tumor size, differentiation, lymph node metastasis, and Tumor Node Metastasis (TNM) stage, was then evaluated." (PMID 37644092, 2023).
metastatic melanoma (1 paper, 2023). A melanoma that has spread from its primary site to another anatomic site. "Repression of genes, including NDUFS1, by a sulfonamide anticancer agent, indisulam, has been shown to improve the survival of patients with metastatic melanoma." (PMID 36675163, 2023).
metastatic tumors (1 paper, 2025). "Indeed, RptorECKO lung metastatic tumors exhibit reduced levels of the ETC complex I subunit, NADH dehydrogenase (ubiquinone) Fe-S protein 1 (NDUFS1)." (PMID 40198126, 2025).
myocarditis (1 paper, 2011). Myocarditis is a condition that is characterized by inflammation of the heart muscle (myocardium). "ATP5b and Ndufs1 were significantly increased in the acute phase of CVB-infected myocarditis mouse heart tissues." (PMID 22014063, 2011). "Among 29 down-regulated proteins that are mainly associated with the generation of precursor metabolites and energy metabolism in EAM heart tissues, only ATP5b and NADH-ubiquinone oxidoreductase (Ndufs1) were also shown to be dysregulated in CVB-infected myocarditis rat heart tissues." (PMID 22014063, 2011).
pancreatic cancer (1 paper, 2026). "Moreover, NDUFS1 and CD147 expressions were highly correlated in pancreatic cancer tissues, and their co-expression was significantly associated with poor patient survival." (PMID 41930324, 2026).
renal cell carcinoma (1 paper, 2023). "Furthermore, other studies suggested using NDUFS1 as a biomarker for the diagnosis of renal cell carcinoma." (PMID 37644092, 2023).
tumor (30 papers, 2014 to 2025). "A mutation in NDUFS1 can, in turn, lead to impairment of electron transport and hence generation of excessive reactive oxygen species, resulting in tumor progression." (PMID 41503337, 2025). "Analysis of tumor heterogeneity using inferHeterogeneity revealed MATH scores > 50 in patients possessing NDUFS1 and SETDB1 mutations, thus showing high intratumoral heterogeneity (p = 0.01)." (PMID 41503337, 2025). "An earlier study has shown that knockdown of wild-type IDH1 triggers a set of tumor suppressor genes, including NDUFS1 (murine Ndufa9), which when mutated is implicated in low survival in certain cancers, and there is a report of high expression of WT-IDH1 in H3K27M tumors." (PMID 35395831, 2022). "Furthermore, compared to the growth delay caused by irradiation alone, NDUFS1 overexpression combined with X-ray irradiation directly shrunk the tumor size in nude mice suggesting a radiosensitization of NDUFS1 overexpression." (PMID 34489398, 2021). "Moreover, NDUFS1 mRNA level is significantly associated with lymphatic and vascular invasion (OR = 8.67, p = 0.004), N stage (OR = 5.50, p = 0.019), tumor differentiation (OR = 0.23, p = 0.039), tumor maximum diameter (OR = 4.00, p = 0.042)." (PMID 33978320, 2021). "RNA-seq data from the TCGA-LUAD cohort were analyzed using the Wilcoxon rank-sum test, demonstrating significantly lower FLNA expression levels (p < 0.001) and elevated NDUFS1 expression (p < 0.001) in tumor tissues compared to normal counterparts." (PMID 40861466, 2025). "Surprisingly, in Pt_ΔND6, even if NDUFS1 levels are comparable between distal and tumor, it is evident the lower presence in Complex I of all analyzed encoded subunits belongs to the Q and P modules." (PMID 40157968, 2025). "The level of NDUFS1 of Pt_ND6-WT was similar when loading the same amount of Complex I from distal and tumor." (PMID 40157968, 2025). "All the genes were highly expressed in tumor samples and except for the genes NDUFS1 and NUBPL, other genes showed apparent differences between the two groups." (PMID 38531953, 2024). "NDUFS1 was the only overlapped NDUFS gene that differentially expressed between tumor and normal tissues in KIRC patients among UALCAN, ENCORI and GEPIA databases." (PMID 37469574, 2023). "To confirm these findings, we further analyzed the NDUFS1 expression in GC by immunohistochemistry (IHC) analysis using tissue microarray (TMA) that included 254 paired GC tumor tissues and adjacent normal gastric tissues." (PMID 37644092, 2023). "Our previous iTRAQ analysis has suggested that the expression of NDUFS1 is downregulated in clinical GC tumor tissues." (PMID 37644092, 2023). "As for protein level, NDUFS1 and FDX1 was also positively correlative with the correlation coefficient in tumor was only 0.40 while in adjacent normal tissues was 0.82, which was consisting with the trend between the difference in NDUFS1 mRNA and protein." (PMID 37469574, 2023). "We analyzed the expression of genes in tumor and normal samples, and the results showed that NDUFS1, NDUFS2, NDUFC1, and EPAS1 were downregulated in CRC, and SLC7A11, OXSM, LRPPRC, NDIFA11, NUBPL, and CONT1 were upregulated in CRC." (PMID 37978247, 2023). "Our biological assays demonstrated that decreased NDUFS1 accelerated GC cell proliferation and metastasis in vitro and in vivo in athymic nude mice, indicating that mitochondrial complex I subunit NDUFS1 was a novel tumor suppressor." (PMID 37644092, 2023). "Our data showed that a low level of NDUFS1 was correlated with large tumor size, poor differentiation, presence of lymph node metastasis, and high TNM stage (P < 0.05)." (PMID 37644092, 2023). "As a result, miR‐3130‐5p directly regulates the expression of NDUFS1 and the corresponding tumor invasiveness, migration and epithelial‐mesenchymal transition (EMT)." (PMID 33978320, 2021).
tumor (continued). "We used qRT‐PCR to investigate the expression levels of miR‐3130‐5p and NDUFS1 mRNA in 43 LUAD tissues from patients who received tumor resections." (PMID 33978320, 2021). "Consistent with previous studies, our study demonstrated NDUFS1 acts as a tumor‐suppressor in the invasion, migration and EMT of LUAD cells." (PMID 33978320, 2021). "Upon subcutaneous engraftment in immunodeficient nude mice, cells with NDUFS1 knockdown were less capable of forming tumor in vivo compared with correspondence control." (PMID 34650055, 2021). "In both aPKC-CAAX and brat tumours we found that knockdown of the complex I subunit, NDUFS1, strongly inhibited tumour growth and decreased overall brain size." (PMID 31513013, 2019). "We used RNAi to knock down subunits of complex I (NDUFS1) or complex V (ATPsynα) in NSCs and tumour cells with a NSC-specific driver, Worniu-GAL4." (PMID 31513013, 2019). "Therefore, it is worth studying the clinical correlation of NDUFS1 expression level with tumor angiogenesis as well as clinical efficacy of Ramucirumab in GC patients." (PMID 37644092, 2023). "Therefore, lower NDUFS1 expression was correlated with advanced tumor grades, patients’ stages and worse subtype in KIRC." (PMID 37469574, 2023). "Together, we speculated that NDUFS1 may reprogram the tumor immune microenvironment via affecting cell metabolism." (PMID 37469574, 2023). "Moreover, we analyzed the NDUFS1 expression based on different tumor grades, patients’ stages and subtypes through digging into UALCAN database." (PMID 37469574, 2023). "At the endpoint (a combined left and right tumor burdenof >1 cm3 or 30 days of growth), xenografts were excised for histology and stained with the nuclear dye Hoechst and GFP antibody to enhance visualization of GFP-labelled NDUFS1-deficient cells." (PMID 36107487, 2022). "Moreover, NDUFS1 overexpression can not only significantly reduce the volume of xenografted tumors after radiotherapy, but also directly inhibit tumor growth in nude mice." (PMID 34489398, 2021). "Therefore, NDUFS1 is a potential tumor‐suppressor targeted by 2q33‐miR‐3130‐5p axis which influences the invasiveness of LUAD." (PMID 33978320, 2021). "In addition, miR‐3130‐5p suppresses the activity of NDUFS1 and thereby promotes tumor invasiveness and possibly migration and EMT hence a potential biomarker of LUAD." (PMID 33978320, 2021). "Assessment of fully-assembled respiratory chain complexes by native immunoblot revealed that neutrophils from tumour bearing mice had increased levels of complexes I (NDUFS1) and IV (MTCO1), and significantly increased complex IV activity by in gel activity assay." (PMID 30504842, 2018). "NDUFS1 may be a novel tumor suppressor and a potential therapeutic target for GC." (PMID 37644092, 2023). "Specifically, an elevation in the expression levels of PRN1, OXSM, SLC3A2, and CD2AP were observed in tumor tissues, while the expression levels of DSTN, FLNA, TLN1, IQGAP1, MYL6, NCKAP1, and NDUFS1 declined in tumor tissues." (PMID 39995998, 2025). "Ndufs1 (NADH:Ubiquinone Oxidoreductase Core Subunit S1; UniProt P28331) is involved in the adaptability of tumor cells to their environment, particularly at low pH." (PMID 38193115, 2024). "The results demonstrated that all 27 disulfrgs, except for NDUFS1, NUBPL, MYH10, and IQGAP1 genes, exhibited significantly higher expression in tumor tissues." (PMID 38831301, 2024). "We conducted IHC stainings of NDUFS1 and ATP5O in PCa and adjacent tumor-free tissue in a cohort of 88 patients who underwent radical prostatectomy." (PMID 34885151, 2021). "Therefore, we preliminarily analyzed the regulatory effect of NDUFS1 on FBLN5 in NDUFS1-overexpressing and -interfering GC cells and their tumor xenografts." (PMID 37644092, 2023). "Moreover, in vivo data further showed that overexpression of NDUFS1 suppressed MKN45 xenograft tumor growth (P < 0.05), whereas knockdown of NDUFS1 accelerated N87 xenograft tumor growth (P < 0.05)." (PMID 37644092, 2023).
tumor (continued). "We detected a response toward one of these neoepitopes (Ndufs1) in one mouse of the i.t. treated group, but the anti-tumor efficacy was not better for this mouse compared to others of the same group." (PMID 29888319, 2018). "In addition, the western blot results of tumor tissues also showed higher PDH and lower HIF-1α in NDUFS1 overexpressing groups combined with or without irradiation." (PMID 34489398, 2021).